PBK (PDZ binding kinase)
Diseases named in the same sentence as PBK in open-access papers (continued):
Sharing a sentence is not in itself a finding about the gene and the disease.
tumor (continued). "In addition, we showed that CDK1/PBK/CHEK1 overexpression promotes GBM tumor aggressiveness, immunosuppression, and progression by recruiting the tumor-promoting immune cells such as the T Cells CD4+ Th2 subtype, MDSCs, and the TAM-M2 subtype." (PMID 38003585, 2023). "The results revealed that high PBK expression was associated with hypoxia, autophagic process and enhanced HIF signaling, while the activation of HIF and the occurrence of autophagy under hypoxia were associated with tumor immune escape." (PMID 37993518, 2023). "In addition, the role and mechanisms of PBK in tumor immunity need to be validated by designing a complete experimental program." (PMID 37993518, 2023). "To test this hypothesis, we genetically altered LIN28B expression in Group 3 MB cells and compared tumor cell viability and growth in vitro and in vivo and we determined the impact on downstream regulation of let‐7 and PBK." (PMID 37341142, 2023). "We next analyzed the PBK/TOPK expression level across four different tumor types of COAD." (PMID 35203508, 2022). "An in vivo study reported that inhibition of PBK could almost completely abolish tumor growth, which made PBK serve as a potentially promising therapeutic target for GBM treatment." (PMID 35800363, 2022). "PBK serves an essential regulatory role in tumor cell proliferation, invasion, and metastasis." (PMID 35906548, 2022). "In the Multivariate Cox regression model, tumor stage (HR = 2.274, 95% CI = 1.538–3.362, P < 0.001) and PBK expression (HR = 1.566, 95% CI = 1.062–2.311, P = 0.024) were likewise confirmed to be independent prognostic factors of overall survival in HCC patients." (PMID 35065633, 2022). "The target PBK/TOPK-binding proteins screened using STRING and PBK/TOPK expression-correlated genes screened using GEPIA2 were included in a series of enrichment analyses to further explore the molecular mechanism of the PBK/TOPK gene in tumorigenesis and tumor immunity." (PMID 34603451, 2021). "This suggests that PBK might be relevant to tumor immunity by regulating the expression levels of these immune checkpoints." (PMID 34859049, 2021). "PDZ-binding kinase (PBK) is known to regulate tumor progression in some cancer types." (PMID 34859058, 2021). "In addition, we explored the correlation between the expression of the PBK/TOPK mRNA and the tumor grade." (PMID 34603451, 2021). "The role of PBK in the tumor immune landscape is still unclear." (PMID 34859049, 2021). "Furthermore, we identified high PBK expression in tumor cells as one of the potential favorable factors for CRC patients." (PMID 35115926, 2021). "Based on these results, PBK/TOPK may influence the prognosis of patients with cancer by modulating tumor immune cell infiltration." (PMID 34603451, 2021). "In order to investigate whether the PBK/CD276 axis plays an important role in tumor immune evasion, we conducted the cytotoxic T-lymphocyte assay." (PMID 33431797, 2021). "All these terms were enriched in the PBK high-expression side, which suggested that high PBK expression mainly involved these signaling pathways, participated in mitosis and the cell cycle, and may also function in promoting tumor cell proliferation." (PMID 34859049, 2021). "PBK expression was positively correlated not only with immune infiltration cells including M2 macrophage, Tregs, CAFs, and MDSCs but also with T-cell exhaustion, which are involved in tumor immune escape." (PMID 34603451, 2021). "We also found that PBK expression is related to cancer immunity: in some cancers, PBK may affect tumor progression by increasing immune cell infiltration into the tumor microenvironment, making it a potential target for cancer immunotherapy." (PMID 34859058, 2021). "To determine whether PBK is involved in immune cell invasion into the tumor microenvironment, we analyzed the correlation between PBK expression and the infiltration of six immune cell types in 32 cancers in the TIMR database." (PMID 34859058, 2021).
tumor (continued). "Whereas PBK expression was low in benign tissue, metastatic tissue had significant higher PBK expression, which predominantly localised in the nucleus of tumour cells (p = 6.4e-08) consistent with increased nuclear localisation observed in high-risk primary PrCa." (PMID 30237440, 2019). "Next, we investigated whether elevated PBK expression affected the tumor response to cisplatin treatment in vivo." (PMID 30778048, 2019). "In men with PrCa, PBK is androgen-regulated and localised in the tumour cell nucleus." (PMID 30237440, 2019). "Overall, PBK/TOPK expression might be related to the cytogenesis of tumor cells, as we found that a lower expression of total PBK/TOPK gave a poorer prognosis for a CRC patient." (PMID 30286126, 2018). "Since the analyses of clinical correlation indicate PBK might be involved in tumor progression, we performed in vitro and in vivo experiments to disclose the role of PBK in HCC." (PMID 28525379, 2017). "Plot of the miR-770-5p and PBK mRNA levels from each tumor tissue showed distinct clustering." (PMID 28333152, 2017). "PBK/TOPK is a growth-factor-regulated kinase, which is constitutively high in tumor cells." (PMID 27347940, 2016). "Current studies implicate PBK/TOPK expression in tumor development, cancer growth, and apoptosis." (PMID 27347940, 2016). "The PDZ binding kinase (PBK), which is up-regulated in various neoplasms and in genistein-treated cells, has been the focus of attention, especially the elucidation of its role in malignant conversion and as a possible therapeutic target in numerous types of cancers." (PMID 18847459, 2008). "Additionally, it has been suggested that increased expression of PBK may promote tumor growth by facilitating p38 activation and aiding cells in overcoming DNA damage." (PMID 38363020, 2024). "Moreover, literature searches revealed that the other hub genes are also associated with tumor development, though the relationship between PBK and these hub genes has not yet been further studied." (PMID 39649886, 2024). "In addition, we have found that PBK may promote tumor proliferation through angiogenesis and F9 may be a predictor of tumor immunotherapy response." (PMID 36685860, 2022). "Therefore, we hypothesized that PBK may be related to angiogenesis and promote tumor proliferation through VEGFR-mediated vascular formation." (PMID 36685860, 2022). "Downregulation of the PBK/TOPK gene can cause the internal structure of a cell to become disordered and leads to a delay in cell cytokinesis during mitosis, thereby reducing the cell viability and expansion capacity and inhibiting the potential for tumor cell generation." (PMID 36171591, 2022). "Also, PBK is downregulated in COAD during increased tumor stages." (PMID 34859049, 2021). "Further investigation may uncover additional organ- or tumor type–specific PBK functions." (PMID 35115926, 2021). "The correlation of PBK/TOPK protein expression with the tumor stage in COAD remains unclear." (PMID 34603451, 2021). "In addition, DNA methylation may play an important role in tumor progression, and PBK/TOPK expression was positively correlated with methyltransferase expression, including DNMT1, DNMT3A, and DNMT3B, in most cancers except CHOL." (PMID 34603451, 2021). "Interestingly, PBK, TTK, BAGE, and CT45A encode proteins termed cancer/testis antigens known to confer a selective advantage to tumor cells by promoting oncogenic processes or permitting evasion of tumor-suppressive mechanisms." (PMID 33239635, 2020). "We next investigated whether PBK affected the tumor growth and metastasis in vivo." (PMID 28525379, 2017).
tumor (continued). "T-LAK cell-originated protein kinase (TOPK/PBK), a member of serine-threonine mitogen-activated protein kinase kinase family, is found highly expressed in certain types of cancer including breast, colon and lung cancer and HCC, and activation of TOPK is closely linked to the tumor development." (PMID 27582549, 2016). "Thus, HI-TOPK-032 appears to arrest tumor growth through inhibition of PBK in vivo." (PMID 26081429, 2015). "Therefore, PBK protein may serve as a potential target for tumor therapy and diagnosis." (PMID 39628686, 2024). "Studies show that a positive feedback loop between PBK and ERK leads to uncontrolled tumor cell proliferation." (PMID 39649886, 2024). "While PBK, RRM2, and DLGAP5 contribute to tumor biology, their roles in genomic stability and mismatch repair are less direct, making them less immediate research priorities in this context." (PMID 39777332, 2024). "Inhibitors of LIN28, such as compound 1632, or PBK, such as HI‐TOPK‐032, can lead to a reduction in tumor growth and cell proliferation." (PMID 37341142, 2023). "We found that CDK1/PBK/CHEK1 overexpression drives the cell cycle, subsequently promoting GBM tumor progression." (PMID 38003585, 2023). "Studies have shown that the selective inhibition of CDK1, PBK, and CHEK1 arrests tumor progression in sarcomas, GBM, prostate, endometrial, and breast cancers by blocking the G2-M phase transition and promoting apoptosis." (PMID 38003585, 2023). "The simultaneous inhibition of CDK1/PBK/CHEK1 will promote the cell cycle arrest, senescence, and apoptosis of GBM, suppressing tumor progression." (PMID 38003585, 2023). "High PBK expression affects the downregulation of CCR6 preventing cells such as effector/memory T cells and DCs from being attracted into the tumor for further tumor immune escape." (PMID 37993518, 2023). "The results showed that the mRNA expression levels of hub genes (PBK, KIF2C, NUF2, KIF20A, RAD51AP1 and DEPDC1) in tumor samples (EAC, ESCC) were significantly higher than in normal samples (P < 0.05)." (PMID 33403046, 2021). "Several PBK-targeting compounds such as HI-TOPK-032, SKLB-C05 and Ginsenoside Rh2 have been reported to suppress tumor growth and/or metastasis of CRC." (PMID 35115926, 2021). "However, the function of PBK in many other tumor types remains unclear." (PMID 34859058, 2021). "Simultaneously, the infiltration levels of tumor-repressing leukocytes, including NK, B, Tfh, CD4+ T cells, and Th17, were negatively correlated with PBK mRNA expression." (PMID 33431797, 2021). "PBK/TOPK is highly and frequently activated in various actively proliferating cells, especially in cancers, and plays an indispensable role in tumor development, metastasis, chemoresistance, and ischemia." (PMID 33670114, 2021). "In this study, we investigated a protein kinase-PDZ Binding Kinase (PBK)/T-LAK Cell-Originated Protein Kinase (TOPK) as a candidate protein regulating prolactin (PRL) secretion and tumor growth of prolactinomas." (PMID 35126305, 2021). "PBK/TOPK is overexpressed in various actively proliferative cells, including malignant tumor cells, as well as normal cells, such as sperm cells." (PMID 33670114, 2021). "PBK, a serine-threonine kinase, was previously reported to phosphorylate p38 MAPK and promote tumor cell proliferation." (PMID 30795783, 2019). "The PBK/TOPK downstream signaling molecules Histone H3 and ERK2 in tumor tissues were also decreased after baicalin treatment." (PMID 30898980, 2019). "Upon cisplatin treatment, the tumor volumes were significantly higher in mice injected with PCMV-PBK cells than in those injected with PCMV cells, and CQ reversed the effect of PBK overexpression." (PMID 30778048, 2019). "A scoring technique was devised attributing a score of +1 to each poor prognostic marker exhibited on immunostaining of individual tumour cores (i.e., high ANLN, high PBK and low PDZK1)." (PMID 23547718, 2013).
tumor (continued). "Additionally, these cells exhibit specific upregulation of CEP55, PBK, BIRC5, STMN1, MT2 A, and CKS1B, all of which are related to tumor inflammatory responses." (PMID 40524208, 2025). "PBK overexpression likely helps them migrate and invade the PBZ, where they could contribute to tumor recurrence." (PMID 36300592, 2023). "Interestingly, treatment with ginsenoside Rh2 also suppresses PDZ-binding kinase/T-LAK cell-originated protein kinase (PBK/TOPK), which retards the proliferation of tumor cells through the ERK1/2 signaling pathway." (PMID 35419278, 2022). "We analyzed the correlations of PBK/TOPK expression with the infiltrating immune cells that exert tumor-killing effect (CD8+, NK cell) and promote tumor immune escape (M2 macrophage, Tregs, CAFs, MDSCs) based on TIMER2.0 to further explore the potential role of PBK in cancer immunity." (PMID 34603451, 2021). "MAD2L1, NCAPG, PBK, and PLK4) was validated using qRT-PCR in MDA-MB-231 and BT-549.Taken together, our data highlighted activation of several tumor suppressor transcriptional regulatory networks in response to DNMT inhibition leading to tumor cell death." (PMID 34565361, 2021). "PBK overexpression groups presented a higher TIDE score, suggesting more T-cell dysfunction and elimination characteristics in the 3 tumors, which again suggested the important role of PBK in tumor immune escape." (PMID 34603451, 2021). "There is a lot of evidence showing that PBK/TOPK could promote the proliferation and migration of tumor cells by activating p38 MAPK." (PMID 35126305, 2021). "Regarding its intracellular distribution, PBK/TOPK is expressed both in the cytoplasm and the nucleus; however, it may be expressed exclusively in the nucleus of tumor cells or in mitosis, particularly around chromosomal surfaces during prophase and metaphase." (PMID 33670114, 2021). "Importantly, an identified PBK inhibitor, HI-TOPK-032, has been shown to inhibit tumor growth, both in vitro and in vivo, making this biomarker interesting for further clinical studies." (PMID 28978135, 2017). "PBK was required for malignant phenotypes of NPC, as PBK depletion by RNAi and inhibition by specific inhibitor HI-TOPK-032 obviously reduced cell proliferation and xenograft tumor growth in mice." (PMID 27049917, 2016). "Furthermore, SW480-derived microvesicles are enriched with CENPE, KIF15, CEP55, CCNA2, NEK2, PBK, and CDK8 that are M-phase-related transcripts involved in tumorigenesis and tumor progression." (PMID 19930720, 2009). "It is clear that PBK overexpression affects T cell activation, downregulation of MHCI-like genes and thus leads to reduced type 1 and 2 interferon γ responses, which prevent T cells from playing their anti-tumor role properly and tumors undergo significant immune escape." (PMID 37993518, 2023). "We first analyzed the expression pattern of PBK in nontumor tissues and different tumor cell lines." (PMID 34859049, 2021). "Although previous studies have reported higher expression of the PBK/TOPK mRNA and protein in tumor tissues than in adjacent noncancerous tissues from different tumors, this study was the first pan-cancer analysis of PBK/TOPK and enabled us to observe the expression across all cancers." (PMID 34603451, 2021). "PBK has been revealed to contribute to the regulation of proliferation and cell cycle progression, whereas whether PBK involves in the tumor immune evasion is not reported so far." (PMID 33431797, 2021). "The present finding that low total PBK/TOPK expression is closely related to poor outcomes might be contrary to a previously hypothesized mechanism, which viewed PBK/TOPK as a gene related to cytogenesis that is overexpressed in tumor cells." (PMID 30286126, 2018).
tumor (continued). "Moreover, PBK has been recognized as a metastasis-promoting kinase that it promotes cell migration by modulating the PI3K/PTEN/AKT pathway in lung cancer and is highly expressed in circulating tumor cells, enabling metastasis of prostate cancer." (PMID 27049917, 2016). "Conclusively, the PBK expression level was positively correlated with trametinib, RDEA119, PD032590, and selumetinib, which indicated that PBK may be positively correlated with the treatment of these chemotherapeutic drugs and may provide a new direction in tumor chemotherapy." (PMID 34859049, 2021). "PBK expression was significant in stages I, II, and III across cancers, and the differences between higher tumor stages were relatively small and not statistically significant." (PMID 34859049, 2021). "PBK/TOPK expression was also analyzed via semi-quantitative RT-PCR and this data closely matched PBK/TOPK protein levels, thereby confirming that PBK/TOPK is expressed exclusively in tumor samples and not in normal prostatic tissue." (PMID 25909225, 2015). "We analyzed the correlation between the PBK expression level and TMB, which showed positive correlation with TMB in 22 types of cancer, including STAD, UCEC, COAD, SARC, READ, MESO, and HNSC, while it is negatively correlated with THYM, which is the only tumor type with negative correlation." (PMID 34859049, 2021).